TBC1D3F (TBC1 domain family member 3F)
Description:
Acts as a GTPase activating protein for RAB5. Does not act on RAB4 or RAB11 (By similarity).
Gene: Protein-coding gene on chromosome 17 (36,428,612 to 36,439,566, reverse strand). Ensembl gene ENSG00000275954.
Subcellular location: Cell membrane
Subcellular location (Human Protein Atlas): Vesicles
Gene Ontology:
Molecular function: protein binding; GTPase activator activity
Cellular component: endosome; membrane; plasma membrane
Genetic constraint (gnomAD): Loss-of-function variants: 3 observed, 3.81 expected, observed/expected ratio (o/e) 0.79, 90% interval 0.35 to 1.75. That is too few expected variants to judge how well the gene tolerates losing a copy. Missense variants: 29 observed, 33.79 expected, observed/expected ratio (o/e) 0.86, 90% interval 0.64 to 1.17. Synonymous variants: 6 observed, 9.82 expected, observed/expected ratio (o/e) 0.61, 90% interval 0.33 to 1.21.
Homologues: Orthologues: chimpanzee TBC1D3B (96% identical). Paralogues in human: TBC1D3 (99% identical), TBC1D3C (99% identical), TBC1D3K (99% identical), TBC1D3D (99% identical), TBC1D3E (99% identical), TBC1D3G (99% identical), TBC1D3I (99% identical), TBC1D3H (99% identical), TBC1D3L (99% identical), TBC1D3B (99% identical), TBC1D26 (30% identical), USP6NL (29% identical), and 33 more.
Diseases named in the same sentence as TBC1D3F in open-access papers:
TBC1D3F is named in the same sentence as 1 disease in open-access papers, as found by Europe PMC text mining. Sharing a sentence is not in itself a finding about the gene and the disease. The quoted sentences say what the papers report.
ovarian carcinoma (1 paper, 2024). A malignant neoplasm originating from the surface ovarian epithelium. "The top gene of positive selection (except for microRNA), TBC1D3F (TBC1 domain family member 3F), was overexpressed in EOC cell lines and primary tumors compared with normal tissues that could be related to ovarian cancer." (PMID 38376367, 2024).